LYSMD4 (LysM domain containing 4)
Synonyms: FLJ33008
Tractability: Antibody: UniProt predicts a signal peptide or a membrane-spanning region.
Gene: Protein-coding gene on chromosome 15 (99,715,697 to 99,733,561, reverse strand). Ensembl gene ENSG00000183060.
Subcellular location: Membrane
Subcellular location (Human Protein Atlas): Cytosol; Actin filaments
Gene Ontology:
Cellular component: membrane
Genetic constraint (gnomAD): Loss-of-function variants: 9 observed, 7.17 expected, observed/expected ratio (o/e) 1.26, 90% interval 0.74 to 1.87. That is too few expected variants to judge how well the gene tolerates losing a copy. Missense variants: 384 observed, 392.77 expected, observed/expected ratio (o/e) 0.98, 90% interval 0.9 to 1.06. Synonymous variants: 143 observed, 156.31 expected, observed/expected ratio (o/e) 0.91, 90% interval 0.8 to 1.05.
Homologues: Orthologues: macaque LYSMD4 (92% identical), dog LYSMD4 (78% identical), pig LYSMD4 (76% identical), rat Lysmd4 (73% identical), guinea pig LYSMD4 (72% identical), chimpanzee LYSMD4 (71% identical), mouse Lysmd4 (70% identical), rabbit LYSMD4 (63% identical), tropical clawed frog lysmd4 (41% identical), zebrafish lysmd4 (36% identical), Drosophila melanogaster CG17985 (20% identical), Caenorhabditis elegans lmd-1 (19% identical). Paralogues in human: LYSMD3 (29% identical), LYSMD1 (14% identical), LYSMD2 (12% identical).